HYCC1 (hyccin PI4KA lipid kinase complex subunit 1)
Description:
Component of a complex required to localize phosphatidylinositol 4-kinase (PI4K) to the plasma membrane. The complex acts as a regulator of phosphatidylinositol 4-phosphate (PtdIns(4)P) synthesis. HYCC1 plays a key role in oligodendrocytes formation, a cell type with expanded plasma membrane that requires generation of PtdIns(4)P. Its role in oligodendrocytes formation probably explains its importance in myelination of the central and peripheral nervous system. May also have a role in the beta-catenin/Lef signaling pathway (Probable).
Synonyms: DRCTNNB1A; FAM126A; HCC; hyccin; HLD5
Tractability: Small molecule: a structure with a bound ligand is known. Antibody: UniProt places it where antibodies can reach, with high confidence; its Gene Ontology location is reachable by antibodies, with high confidence; the Human Protein Atlas places it where antibodies can reach. PROTAC: ubiquitination databases record sites on it.
Gene: Protein-coding gene on chromosome 7 (22,889,371 to 23,014,130, reverse strand). Ensembl gene ENSG00000122591.
Subcellular location: Cytoplasm, cytosol; Cell membrane
Subcellular location (Human Protein Atlas): Cytosol; Plasma membrane
Gene Ontology:
Molecular function: protein binding
Biological process: phosphatidylinositol phosphate biosynthetic process; protein localization to plasma membrane; myelination
Cellular component: cytosol; plasma membrane; neuron projection
Genetic constraint (gnomAD): Loss-of-function variants: 15 observed, 30.99 expected, observed/expected ratio (o/e) 0.48, 90% interval 0.32 to 0.75. The upper end of that interval is the gene's LOEUF score, 0.75, which puts it in group 3 of 6, group 1 being the genes least tolerant of losing a copy. Missense variants: 393 observed, 439.94 expected, observed/expected ratio (o/e) 0.89, 90% interval 0.82 to 0.97. Synonymous variants: 157 observed, 156.06 expected, observed/expected ratio (o/e) 1.01, 90% interval 0.88 to 1.15.
Gene-disease validity (ClinGen):
ClinGen rates the evidence that HYCC1 causes each of these diseases.
hypomyelinating leukodystrophy 5 (autosomal recessive): Definitive. Hypomyelination-congenital cataract is characterized by the onset of cataract either at birth or in the first two months of life, delayed psychomotor development by the end of the first year of life and moderate intellectual deficit.
Homologues: Orthologues: chimpanzee HYCC1 (99% identical), macaque HYCC1 (99% identical), dog HYCC1 (97% identical), pig HYCC1 (97% identical), guinea pig HYCC1 (97% identical), rabbit HYCC1 (94% identical), rat Hycc1 (88% identical), tropical clawed frog hycc1 (75% identical), mouse Hycc1 (65% identical), zebrafish hycc1 (62% identical), Drosophila melanogaster Hyccin (28% identical), Caenorhabditis elegans D1069.3 (22% identical). Paralogues in human: HYCC2 (52% identical).
Diseases named in the same sentence as HYCC1 in open-access papers:
HYCC1 is named in the same sentence as 19 diseases in open-access papers, as found by Europe PMC text mining. Sharing a sentence is not in itself a finding about the gene and the disease.
HYCC1 shares sentences with these, for which no sentence is quoted: cancer (3 papers); pancreatic cancer (2); schizophrenia (2); Tumor (2); Alzheimer disease (1); brain hemorrhages (1); cardiomyopathy (1); cerebral amyloid angiopathy (1); chronic kidney disease (1); colitis (1); colorectal cancer (1); congenital cataracts (1); dementia (1); developmental delay (1); hypomyelinating leukodystrophy (1); kidney diseases (1); neurological disorders (1); pancreatic adenocarcinoma (1); Parkinson disease (1).